TNXB (tenascin XB)
Description:
Appears to mediate interactions between cells and the extracellular matrix. Substrate-adhesion molecule that appears to inhibit cell migration. Accelerates collagen fibril formation. May play a role in supporting the growth of epithelial tumors.
Synonyms: TN-X; HXBL; TNX; TNXB1; TNXB2; XB; TNXBS; XBS; EDS3; EDSCLL; EDSCLL1; TENX; VUR8
Tractability: Antibody: UniProt places it where antibodies can reach, with medium confidence; UniProt predicts a signal peptide or a membrane-spanning region; its Gene Ontology location is reachable by antibodies, with medium confidence.
Gene: Protein-coding gene on chromosome 6 (32,041,153 to 32,115,334, reverse strand). Ensembl gene ENSG00000168477.
Subcellular location: Secreted, extracellular space, extracellular matrix
Subcellular location (Human Protein Atlas): Vesicles; Predicted to be secreted
Pathways (Reactome):
Extracellular matrix organization: ECM proteoglycans
Gene Ontology:
Molecular function: collagen fibril binding; protein binding; extracellular matrix structural constituent; heparin binding; integrin binding; collagen binding
Biological process: collagen metabolic process; elastic fiber assembly; positive regulation of collagen fibril organization; actin cytoskeleton organization; cell adhesion; neuron projection development; positive regulation of cell fate determination; regulation of cell adhesion; regulation of cell differentiation
Cellular component: extracellular exosome; extracellular matrix; extracellular region; tenascin complex
Genetic constraint (gnomAD): Loss-of-function variants: 177 observed, 297.64 expected, observed/expected ratio (o/e) 0.59, 90% interval 0.52 to 0.67. The upper end of that interval is the gene's LOEUF score, 0.67, which puts it in group 2 of 6, group 1 being the genes least tolerant of losing a copy. Missense variants: 4,467 observed, 5,055.1 expected, observed/expected ratio (o/e) 0.88, 90% interval 0.86 to 0.91. Synonymous variants: 2,072 observed, 2,137 expected, observed/expected ratio (o/e) 0.97, 90% interval 0.93 to 1.
Homologues: Orthologues: macaque TNXB (90% identical), pig TNXB (80% identical), mouse Tnxb (75% identical), rat AABR07044388.2 (74% identical), guinea pig TNXB (59% identical), zebrafish tnxba (7% identical), tropical clawed frog tnxb (5% identical). Paralogues in human: TNC (20% identical), TNR (11% identical), TNN (9% identical), FN1 (8% identical), ANGPT1 (4% identical), FCN2 (3% identical), FCN1 (3% identical), ANGPT2 (3% identical), FGL2 (3% identical), ANGPTL2 (3% identical), ANGPT4 (3% identical), FIBCD1 (3% identical), and 13 more.
Diseases named in the same sentence as TNXB in open-access papers:
TNXB is named in the same sentence as 125 diseases in open-access papers, as found by Europe PMC text mining. Sharing a sentence is not in itself a finding about the gene and the disease. The quoted sentences say what the papers report.
Ehlers-Danlos syndrome (35 papers, 2008 to 2026). The Ehlers–Danlos syndromes (EDS) are a clinically and genetically heterogeneous group of heritable connective tissue disorders (HCTDs) characterized by joint hypermobility, skin hyperextensibility, and tissue fragility. "In consequence, the exact functional effects of genetic-genomic variants in the TNXB gene region and its relevance for hypermobility and different types of Ehlers-Danlos syndromes beyond clEDS remain to be clarified." (PMID 39629471, 2024). "A mutation in TNXB has also been associated with connective tissue laxity that is part of an Ehler-Danlos Syndrome-like phenotype." (PMID 37645058, 2023). "In human, variants in TNXB cause a rare monogenic autosomal recessive subtype of Ehlers-Danlos syndromes (EDSs) with hyperextensible and fragile skin." (PMID 34837693, 2021). "To date, at least nine kinds of chimeric TNXA/TNXB genes have been identified and associated with Ehlers-Danlos syndrome as well as with CAH." (PMID 30559721, 2018). "Although mutations in the TNXB gene are responsible for the Ehlers-Danlos Syndrome, it is unlikely that this gene is responsible for the observed effect in HIV-1 plasma viral load." (PMID 19107206, 2008). "Loss of the Tenascin X protein caused by mutations in the TNXB gene is associated with the development of the connective tissue disorder known as Ehlers-Danlos syndrome and patients with Ehlers-Danlos syndrome have a more than threefold increased risk for depression." (PMID 39897774, 2025). "Mutations in TNXB are the cause of a variant of Ehlers-Danlos syndrome, a disease associated with impaired collagen synthesis and manifested as joint hypermobility, overstretching of the skin and general fragility of the connective tissue.TNXB." (PMID 39512309, 2024). "Deficiency of TNXB has been associated with the connective tissue disorder Ehlers-Danlos syndrome." (PMID 37924108, 2023). "TNXB deficiency is associated with Ehlers Danlos syndrome (EDS)." (PMID 35282436, 2022). "This is considered a milder form of Ehlers-Danlos syndrome, in which TNXB locus is also implicated." (PMID 33192958, 2020). "Unusual digital anomalies seem confirmed as possibly peculiar of TNXB-clEDS, while vascular fragility could be more than a chance association also in this Ehlers-Danlos syndrome type." (PMID 31775249, 2019). "Mutations in TNXB are associated with the hypermobility type of Ehlers-Danlos syndrome." (PMID 28346524, 2017). "TNXB deficiency leads to Ehlers-Danlos Syndrome (EDS) and up to 10% of CAH patients also have EDS, an entity called CAH-X." (PMID 35282436, 2022). "If the deletion results in loss of functional TNXB because of TNXB-TNXA fusion, the resulting phenotype combines CAH with Ehlers-Danlos syndrome, denoted CAH-X syndrome." (PMID 39629471, 2024). "Ehlers-Danlos syndrome (EDS), characterized by two autosomal recessive mutations in the TNXB gene, leads to complete deficiency of tenascin-X: patients typically have the classical hypermobile type of EDS, with a characteristically large range of joint movements." (PMID 36264454, 2023). "TNXB-related classical-like Ehlers-Danlos syndrome (TNXB-clEDS) is an ultrarare type of Ehlers-Danlos syndrome due to biallelic null variants in TNXB, encoding tenascin-X." (PMID 31775249, 2019). "Heterozygous loss of TNXB was claimed as a cause of hypermobile Ehlers-Danlos-Syndrome but this association has not been confirmed." (PMID 39629471, 2024). "In OMIM, TNXB was a pleiotropic gene of Ehlers-Danlos syndrome and Vesicoureteral reflux diseases." (PMID 26253105, 2015). "Co-occurring CYP21A2 and TNXB variants cause CAH-X syndrome, presenting with combined 21OHD and Ehlers-Danlos syndrome (EDS) features (~10% of 21OHD cases)." (PMID 41180189, 2025).
Ehlers-Danlos syndrome (continued). "While TNXB-EDS is characterized by autosomal recessive inheritance, it is important to note that CAH-X syndrome, which involves hypermobility type Ehlers-Danlos syndrome (EDS) linked to mutations in TNXB, follows an autosomal dominant inheritance pattern." (PMID 39512309, 2024). "TNXB (tenascin XB) localizes to the major histocompatibility region on chromosome 6 and encodes an ECM glycoprotein and has been associated to classic Ehlers-Danlos syndrome (EDS), a connective tissue disorder with scoliosis as one characteristic of the phenotype." (PMID 34208743, 2021). "Not included in our analysis were other genes that contribute to Ehlers-Danlos syndrome, which are not directly related to fibrillar collagens, including TNXB, which encodes for tenascin X, an ECM glycoprotein involved in matrix maturation and wound healing." (PMID 28346524, 2017). "No direct link between CNN1 or CDC42EP2 could be made with TNXB or Classical-like Ehlers-Danlos Syndrome (cEDS) through a literature search." (PMID 39480826, 2024). "This rare chimera is characterized by a 120-bp deletion in exon 35 of TNXB and results in TNXB haploinsufficiency and disrupted TGF-β signaling; when found in the homozygous state, it leads to a contiguous gene syndrome consisting of CAH and Ehlers-Danlos syndrome (EDS)." (PMID 36264454, 2023).
congenital adrenal hyperplasia (13 papers, 2019 to 2026). Congenital adrenal hyperplasia (CAH) is an inherited endocrine disorder caused by a steroidogenic enzyme deficiency that is characterized by adrenal insufficiency and variable degrees of hyper or hypo androgyny manifestations, depending of the type and the severity of the disease. "Dr. Deborah P. Merke and others demonstrated that biallelic TNXB variants caused Ehlers‒Danlos syndrome in patients with congenital adrenal hyperplasia." (PMID 37323683, 2023). "This latter deletion is similar to others in this highly variable and repetitive region that are known to cause the formation of the chimeric gene TNXA/TNXB, which may lead to congenital adrenal hyperplasia in combination with connective tissue dysplasia." (PMID 34946907, 2021). "Tenascin-X (TNX) is a large extracellular matrix protein discovered because its TNXB gene overlaps the CYP21A2 gene encoding steroid 21-hydroxylase (P450c21), whose mutations cause congenital adrenal hyperplasia (CAH)." (PMID 33505400, 2020). "CAH-X is a hypermobility-type Ehlers–Danlos syndrome connective tissue dysplasia affecting approximately 15% of patients with 21-hydroxylase deficiency (21-OHD) congenital adrenal hyperplasia (CAH) due to contiguous deletion of CYP21A2 and TNXB genes." (PMID 36833192, 2023). "Approximately 10% of patients with congenital adrenal hyperplasia (CAH) due to 21-hydroxylase deficiency carry a mutation that disrupts CYP21A2 and the flanking TNXB gene resulting in CAH-X, a contiguous gene deletion syndrome." (PMID 31666125, 2019). "The term CAH-X was coined to describe a subset of patients with congenital adrenal hyperplasia (CAH) who display the hypermobility phenotype of Ehlers–Danlos syndrome (hEDS) due to the monoallelic presence of a CYP21A2 deletion extending into the TNXB gene." (PMID 35807105, 2022). "NAHR-mediated deletion between TNXB and TNXA leads to loss of CYP21A2, the causal gene of autosomal recessive 21-hydroxylase deficiency (classical congenital adrenal hyperplasia, CAH), as well as C4B, absence of which may contribute to reduced complement 4 production." (PMID 39629471, 2024).
systemic lupus erythematosus (8 papers, 2013 to 2021). An autoimmune multi-organ disease typically associated with vasculopathy and autoantibody production. "This SNP was intronic to the gene Tenascin XB (TNXB; a gene previously implicated in systemic lupus erythematosus), and positioned just 83 kb from the previously published peak of association for AD within the MHC (rs176095)." (PMID 23886662, 2013). "A SNP in human TNXB has been associated with systemic lupus erythematosus, although its role in autoimmunity remains unclear." (PMID 34440439, 2021). "A SNP in human TNXB has been associated with another autoimmune condition, systemic lupus erythematosus, in a Japanese cohort, although the role of TNXB in autoimmunity remains unclear." (PMID 31443497, 2019). "On the other hand, an SNP in the 5’ flanking region of TNXB has been reported to be associated with systemic lupus erythematosus (SLE)." (PMID 33335533, 2020). "In skin, there were four core-ASE genes, including TNXB, which is related to the pathogenesis of systemic lupus erythematosus and RPS8, which is involved in resistance to hemoprotozoal diseases that cause economic losses among sheep and goats in tropical and subtropical regions." (PMID 30891061, 2019). "For instance, it is tempting to speculate, based on the results of our study that lupus patients expressing lower levels of the TNXB gene are likely to benefit more from caloric restriction." (PMID 31506438, 2019).
breast carcinoma (7 papers, 2011 to 2024). "The over-expression of TNXB mRNA correlates with the long survival of the breast cancers patients, whereas its down-regulation is linked to shorter time of survival." (PMID 32817625, 2020). "As expected, the expression level of TNXB mRNA were significantly associated with the clinical outcomes of lung adenocarcinoma (P = 0.0014) and breast carcinoma (P = 0.0234) patients." (PMID 32817625, 2020). "Decreased levels of CASP8, DDX58, CPNE1, ULK3, PARK7, and BTN2A1, as well as increased levels of TNFRSF9, TNXB, DNPH1, and TLR1, were linked to an elevated risk of breast cancer." (PMID 39351539, 2024). "In the case of TNXB, the expression of this gene has been analyzed in breast cancer, and a correlation between high TNXB expression and good survival prognosis has been found." (PMID 36338974, 2022). "Hypoxic induction of the tenascin-X (TNXB) gene in the breast cancer cell line MCF-7 involves another type of Sp1 activation mechanism." (PMID 26703734, 2015). "Interestingly, expression levels of TNN and TNXB were significantly lower in breast cancer tissues." (PMID 32817625, 2020). "The analysis showed that TNXB was upregulated in patients with bladder cancer (BLCA), cervical cancer (CESC), colon cancer (COAD), and breast cancer (BRCA), while SPON1 was upregulated in patients with LNM in thyroid cancer (THCA) and bladder cancer." (PMID 36520032, 2023). "In these terms, aside from the genes COL4A6, COL6A2 and COL14A1 belonging to the collagen family, Tenascin-X (TNXB), which was described as a metastasis signature in breast cancer, was also up-regulated in our experiment but has not previously been reported for gastric cancer." (PMID 21435268, 2011).
rheumatoid arthritis (5 papers, 2017 to 2024). A chronic, systemic autoimmune disorder characterized by inflammation in the synovial membranes and articular surfaces. "Meanwhile, TNXB, a vital component of synovium, was significantly expressed in rheumatoid arthritis synovium by immunofluorescence labeling, showing that inflammation can promote TNXB production." (PMID 39883516, 2024). "In addition, DNA methylation of TNXB has also been reported in whole blood from rheumatoid arthritis patients and in retinal pigment epithelium from patients with age-related macular degeneration." (PMID 38819423, 2024). "However, increased expression of TNXB has been found in synovial cells of OA and rheumatoid arthritis (RA) patients, suggesting the complex and mixed roles of TNXB in joint diseases." (PMID 36680176, 2022).
21-hydroxylase deficiency (4 papers, 2019 to 2025). "TNXB haploinsufficiency has also been documented among a cohort of CAH patients with a 21-hydroxylase deficiency due to the gene’s 3′ overlap with CYP21A2, a condition known as CAH-X syndrome." (PMID 40650310, 2025).
age-related macular degeneration (4 papers, 2017 to 2024). Age-related loss of vision in the central portion of the retina (macula), secondary to retinal degeneration. "The third is rs12153855 in the TNXB gene of the human leukocyte antigen (HLA) region, where the derived allele is associated with age-related macular degeneration and atopic dermatitis." (PMID 39078618, 2024).
colorectal cancer (4 papers, 2010 to 2025). A primary or metastatic malignant neoplasm that affects the colon or rectum. "Third, although our in vitro experiments suggest a regulatory role of DNA methylation on TNXB expression, further functional studies are needed to determine the causal relationship between TNXB dysregulation and colorectal cancer pathogenesis." (PMID 40806327, 2025). "In particular, in vivo experiments using mouse models and advanced 3D culture systems (e.g., organoids) would help to better understand the biological relevance and therapeutic potential of TNXB in the context of colorectal cancer." (PMID 40806327, 2025). "Consistent with our results, Barrow and colleagues reported that TNXB is highly differentially methylated in active smokers diagnosed with colorectal cancer." (PMID 37048094, 2023). "Future studies are needed to determine whether restoring TNXB expression via demethylating agents or epigenome-editing strategies can produce therapeutic benefits in colorectal cancer models." (PMID 40806327, 2025).
gastric cancer (4 papers, 2011 to 2023). A primary or metastatic malignant neoplasm involving the stomach. "Inhibiting TNXB function using specific antibody significantly reduced gastric cancer cell migration." (PMID 36520032, 2023). "Experimental validation and functional studies indicate that TNXB may be involved in gastric cancer cell migration and spreading." (PMID 36520032, 2023). "Furthermore, treating gastric cancer cells with anti‐TNXB antibody significantly reduced cell migration." (PMID 36520032, 2023). "We selected two gastric cancer cell lines HGC27 and MGC803 in which TNXB was highly expressed to explore the function of TNXB in cell migration." (PMID 36520032, 2023). "These analyses suggested that TNXB and SPON1 may play important roles in tumor infiltrating immune cells, particularly macrophages, in gastric cancer." (PMID 36520032, 2023). "Aberrant methylation at the genes B3GATL4 (6p21.3), TNXB (6p21.3), TRIM31 (6p21.3), LY6G5C (6p21.33), KIAA1949/PPP1R18 (6p21.3), and GNL1 (6p21.3) identified in NPC was also hypermethylated in EBV-positive gastric cancers compared to EBV-negative gastric cancers (FDR < 1.6 × 10−90)." (PMID 25924914, 2015). "Interestingly, Spondin‐1 (SPON1) and Tenascin‐X (TNXB), two proteins that have not been associated with gastric cancer before, showed significant upregulation, consistent with our proteomic findings." (PMID 36520032, 2023).
melanoma (4 papers, 2015 to 2025). A malignant, usually aggressive tumor composed of atypical, neoplastic melanocytes. "Many of these downregulated proteomic cargoes in melanoma sEVs, including collagens (COL1A1, COL3A1, COL6A1–A3, and COL14A1), matrix-associated proteoglycans (DCN, LUM, FMOD, OGN, and PRELP), and structural regulators (TNXB and PCOLCE), are key components of ECM organization and tensile strength." (PMID 41271007, 2025).
schizophrenia (4 papers, 2014 to 2020). A major psychotic disorder characterized by abnormalities in the perception or expression of reality. "TNXB has also been suggested to be associated with schizophrenia based on multiple studies, though the data are controversial, and virtually the entire 1st exon of TNXB is hypomethylated with age." (PMID 25010591, 2014). "TNX is expressed in leptomeninges and choroid plexus, suggesting neurologic roles: TNXB single nucleotide polymorphisms are associated with schizophrenia, and Tnxb-knockout mice have increased anxiety, improved memory, and higher sensorimotor coordination than controls." (PMID 33505400, 2020).
asthma (3 papers, 2020 to 2025). "Although TNXB has only been reported to associate with eczema, it may be very important for asthma and hay fever." (PMID 32373153, 2020).
ovarian carcinoma (3 papers, 2010 to 2024). A malignant neoplasm originating from the surface ovarian epithelium. "TNXB, exhibiting the largest molecular proportions among the tenascins, shows a high correlation with CA125 and has been proposed as a potential biomarker for early ovarian cancer diagnosis." (PMID 38918474, 2024).
psoriasis (3 papers, 2024 to 2025). An autoimmune condition characterized by red, well-delineated plaques with silvery scales that are usually on the extensor surfaces and scalp. "Based on the GWAS data, further MR analysis and colocalization analysis genetically predicted that AIF1, FCGR3A, NEU1, HSPA1A, TNXB (Tenascin XB), and ABO were associated with psoriasis risk." (PMID 39883516, 2024). "MR analyses unveiled 19 unique circulating proteins that were associated with psoriasis, among which only AIF1, FCGR3A, NEU1, HSPA1A, TNXB, and ABO were the potential proteins that interacted with psoriasis risk after being analyzed with high evidence of colocalization (PP.H4 > 0.9)." (PMID 39883516, 2024). "According to this study, NEU1, TNXB, and ABO were also related to psoriasis risk." (PMID 39883516, 2024). "Patients with psoriasis have hypomethylated human leukocyte antigen (HLA)-DMA and G protein-coupled receptor 128 (GPR128) genes, but they have hypermethylated tenascin-XB (TNXB) and macrophage stimulating 1 receptor (MST1R) genes." (PMID 40182929, 2025).